KRT8P3 (keratin 8 pseudogene 3)
Gene: Processed pseudogene on chromosome 8 (61,578,220 to 61,579,668, forward strand). Ensembl gene ENSG00000254285.
Diseases named in the same sentence as KRT8P3 in open-access papers:
KRT8P3 is named in the same sentence as 2 diseases in open-access papers, as found by Europe PMC text mining. Sharing a sentence is not in itself a finding about the gene and the disease.
KRT8P3 shares sentences with these, for which no sentence is quoted: ovarian serous cystadenocarcinoma (1 paper); uterine corpus endometrioid carcinoma (1).